SEMA7A (semaphorin 7A (JohnMiltonHagen blood group))
Diseases named in the same sentence as SEMA7A in open-access papers (continued):
Sharing a sentence is not in itself a finding about the gene and the disease.
chronic asthma (1 paper, 2023). An asthma that is characterized by the development of persistent airway inflammation and recurrent attacks of breathlessness and wheezing, which vary in severity and frequency. "Our research showed that Sema7a and its receptor integrin-β1 were overexpressed in lung tissue in OVA-treated mice (P < 0.01); treatment with anti-Sema7a was effective in alleviating AR in the model of chronic asthma." (PMID 38022556, 2023). "Collectively, these findings may provide insight into the multifaceted role of Sema7a in chronic asthma." (PMID 38022556, 2023). "Therefore, new therapeutic approaches for the treatment of chronic asthma, could be aided by the development of agents that target the Sema7a." (PMID 38022556, 2023). "Our findings suggest that Sema7a may play a fundamental role in AR by inducing EMT through the FAK and ERK1/2 signaling pathway in HBECs and mice model of chronic asthma." (PMID 38022556, 2023).
chronic obstructive pulmonary disease (1 paper, 2020). A chronic and progressive lung disorder characterized by the loss of elasticity of the bronchial tree and the air sacs, destruction of the air sacs wall, thickening of the bronchial wall, and mucous accumulation in the bronchial tree. "In human studies, Sema7A has been shown to be involved in chronic inflammatory diseases like chronic obstructive pulmonary disease (COPD) and RA." (PMID 32210960, 2020).
COVID-19 (1 paper, 2023). A disease caused by infection with severe acute respiratory syndrome coronavirus 2. "In conclusion, we provide the first evidence that SEMA3A, SEMA3C, SEMA3F and SEMA7A can be considered as new biomarkers of COVID-19 severity." (PMID 37893159, 2023). "In contrast, serum concentrations of SEMA3F and SEMA7A positively correlated with COVID-19 severity, with the highest levels in patients with critical COVID-19." (PMID 37893159, 2023). "Concentrations of the serum semaphorins SEMA3A, SEMA3C, SEMA3F, SEMA4D and SEMA7A were detectable in all patients with COVID-19." (PMID 37893159, 2023). "While SEMA3A was decreased, SEMA3C, SEMA3F and SEMA7A were increased in COVID-19." (PMID 37893159, 2023). "To summarize, the SEMA3F and SEMA7A in COVID-19 might regulate vascular permeability and cytoskeletal remodeling along with neutrophil migration and retention in inflamed tissue, which leads to the amplification of inflammation." (PMID 37893159, 2023). "Furthermore, we showed an association of semaphorin levels with COVID-19 severity; SEMA3F and SEMA7A were higher in critical COVID-19, while SEMA3A and SEMA3C negatively correlated with COVID-19 severity and were lower in the critical group." (PMID 37893159, 2023). "In conclusion, we have shown that patients with COVID-19 have different expressions of SEMA3A, SEMA3C, SEMA3F and SEMA7A than healthy controls, which correlate with disease severity and outcomes." (PMID 37893159, 2023).
edema (1 paper, 2021). An abnormal accumulation of fluid beneath the skin, or in one or more cavities of the body. "In the study of acute lung injury caused by seawater aspiration, Sema7a contributed to seawater-induced pulmonary edema and inflammation via the Plexin C1/β1 integrin pathway." (PMID 34007409, 2021).
Hypertension (1 paper, 2019). The presence of chronic increased pressure in the systemic arterial system. "Furthermore, in multivariate logistic analyses, increased serum Sema7A was significantly associated with the risk of AAS while controlling some important conventional CVD risk factors including hypertension, BMI, FBG, TC, TG, HDL‐C, LDL‐C, current smoking and alcohol consumption." (PMID 30729666, 2019).
hyperthyroidism (1 paper, 2014). Overactivity of the thyroid gland resulting in overproduction of thyroid hormone and increased metabolic rate. "As already reported the newborn Mct8KO mice showed an unexpected cerebral cortex hyperthyroidism as reflected in the expression of the thyroid hormone-regulated genes Hr, Sema7a, and Klf9, which is not due to immaturity of the brain barriers." (PMID 24819605, 2014).
intrahepatic cholestasis (1 paper, 2025). A cholestasis characterized by impairment of the bile flow caused by obstruction located in the liver. "More recent hepatobiliary focussed publications identified mutations in Sema7a causing a gain of function, progressing disease; non-alcoholic fatty liver disease (NAFLD) and intrahepatic cholestasis." (PMID 40114253, 2025).
Lewis lung carcinoma (1 paper, 2025). "In this study, by using bioinformatics analysis and an established Lewis lung carcinoma mouse model, we found that SEMA7A was upregulated in the patients with NSCLC and was positively correlated with the tumor progression and poor prognosis." (PMID 41019072, 2025). "In addition, a progressively increased expressions of SEMA7A mRNA were detected in the tumor tissues of Lewis lung carcinoma (LLC) tumor-bearing mice." (PMID 41019072, 2025).
metastatic melanoma (1 paper, 2012). A melanoma that has spread from its primary site to another anatomic site. "A recent study has revealed the role of Sema7A in inhibiting cancer cell invasion by inactivation of cofilin through plexin-C1, which is consistent with the observation of a downregulation of Sema7A in metastatic melanoma cells." (PMID 23050142, 2012).
monocyte leukemia (1 paper, 2023). "To confirm the function of SEMA7A in monocytic leukemia cells, we induced HERV-K119 env gene KO in another monocytic leukemia cell line, U937." (PMID 37958549, 2023). "Because the SEMA7A gene is proposed to be a crucial target of the HERV-K env gene KO according to mRNA sequencing analysis, an overexpression vector for the SEMA7A gene was introduced into THP-1 monocyte leukemia cells to analyze its function in THP-1 cells." (PMID 37958549, 2023).
nosocomial infection (1 paper, 2023). An infection acquired in a hospital or other healthcare setting. "Patients who developed nosocomial infections had significantly higher levels of SEMA3F (6.0 ng/mL, IQR 4.5–6.4 vs. 4.5 ng/mL, IQR 3.9–5.6, p = 0.0411) and SEMA7A (2.8 ng/mL, IQR 1.90–4.2 vs. 1.3 ng/mL, IQR 0.59–1.9, p = 0.0005)." (PMID 37893159, 2023).
osteoarthritis (1 paper, 2017). A noninflammatory degenerative joint disease occurring chiefly in older persons, characterized by degeneration of the articular cartilage, hypertrophy of bone at the margins and changes in the synovial membrane. "Soluble Sema7A (sSema7A) levels in the serum and synovial fluid from patients with RA or osteoarthritis, as well as cytokine secretions, were analyzed with an enzyme-linked immunosorbent assay." (PMID 28109308, 2017).
squamous cell carcinoma (1 paper, 2023). A carcinoma arising from squamous epithelial cells. "What is more, it has been reported that SEMA7A promotes growth and migration of squamous cell carcinoma (OTSCC) by regulating the TGF‐β‐induced EMT signaling pathway in OTSCC cells, which provides a new interconnection between SEMA7A and the TGF‐β‐induced EMT signaling pathway." (PMID 36705403, 2023).
syphilis (1 paper, 2024). A contagious bacterial infection caused by the spirochete Treponema pallidum. "Using multicenter ELISA validations, we selected three biomarkers (SEMA7A, SERPINA3, and ITIH4) and confirmed their efficacy in distinguishing NS from syphilis and other brain diseases, including infectious diseases." (PMID 38380496, 2024).
tuberculosis (1 paper, 2025). A chronic, recurrent infection caused by the bacterium Mycobacterium tuberculosis. "We found that SEMA7A expression was upregulated in both lung tissues and blood samples of tuberculosis patients." (PMID 40182927, 2025). "The discovery of these six mRNAs (NEDD4, PLTP, RNASEL, SEMA7A, TAPBP, and THBS1) not only reveals critical molecular mechanisms underlying immune regulation in tuberculosis but also establishes a robust theoretical foundation for advancing diagnostic and therapeutic strategies." (PMID 40182927, 2025). "NEDD4, PLTP, RNASEL, SEMA7A, TAPBP, and THBS1 were combined into a 6-mRNA feature panel for diagnosis of tuberculosis." (PMID 40182927, 2025). "The results showed that PLTP, RNASEL, SEMA7A, and TAPBP were upregulated in the whole blood of tuberculosis patients, while NEDD4 and THBS1 were downregulated." (PMID 40182927, 2025).
tumor (39 papers, 2014 to 2025). "SEMA7A is upregulated in BC compared to normal tissue in several independent data sets, and highly SEMA7A-expressing tumours were associated with worse overall survival and with early metastases." (PMID 37685898, 2023). "The loss of Sema7A expression by tumor cells reduced their potential for invasion and their ability to activate β1-integrin receptor-related signaling pathways." (PMID 30134791, 2018). "In fact, SEMA7A may increase the polarization of tumor-associated macrophages (TAMs) toward the M2 phenotype in an ITGB1-dependent manner." (PMID 41019072, 2025). "Knockdown of SEMA7A can diminish tumor growth, suggesting SEMA7A may be a risk factor for the tumorigenesis and progression of NSCLC." (PMID 41019072, 2025). "A question that remains unanswered is whether sustained expression of SEMA7A is causative for malignancy or whether SEMA7A expression in the tumor influences normal adjacent cells to express SEMA7A thereby promoting tumor progression and metastasis." (PMID 34561423, 2021). "Taken together, these data suggest a clinically relevant mechanism by which SEMA7A and a6-integrin may promote cellular phenotypes associated with tumor progression and chemoresistance." (PMID 34561423, 2021). "We reveal that SEMA7A regulates normal pubertal development in part by increasing the type of macrophages that are likely promote epithelial and tumor cell invasion." (PMID 40470186, 2025). "This is likely due to SEMA7A regulating macrophage-mediated collagen remodeling such as promoting protease activity at the tumor border which was decreased with SmAbH1 treatment." (PMID 40470186, 2025). "In this study, by using bioinformatics analysis and an experimental murine tumor model, we found that the expression levels of SEMA7A were elevated in the human NSCLC and positively correlated with the poor prognosis." (PMID 41019072, 2025). "Meanwhile, the invasion and migration activities of these tumor cells were markedly reduced after silencing the SEMA7A gene." (PMID 41019072, 2025). "In this study, by using bioinformatics analysis and an experimental murine tumor model, we found that SEMA7A was highly expressed in the tumor tissues of the patients with NSCLC, and the level of SEMA7A was positively correlated with poor survival." (PMID 41019072, 2025). "Recent findings have identified SEMA7A as a tumor promoter, accelerating tumor growth, increasing invasiveness, and promoting adhesion to tumor-associated extracellular matrices." (PMID 40647379, 2025). "Meanwhile, an elevated SEMA7A protein levels were detected in the tumor tissues on day 21 after tumor implantation." (PMID 41019072, 2025). "We demonstrate that macrophage-mediated matrix remodeling is facilitated in part by a collagen, COX-2, SEMA7A signaling axis initiated from epithelial and tumor cells in the mammary gland." (PMID 40470186, 2025). "To validate the IHC approach in ACC tumor samples, we compared the protein and RNA expression levels of SEMA7A in the NCI-ACC samples." (PMID 40647379, 2025). "The expression of SEMA7A and SEMA4D was associated with immunological and metabolic processes occurring within the tumor microenvironment." (PMID 39329961, 2024). "Through RNA-seq of HNSCC samples and validation with a tissue microarray, we identified the overexpression of SEMA7A in tumor samples and the subsequent poorer clinical outcome." (PMID 38548747, 2024). "This study demonstrated that semaphorin 7A (SEMA7A) expression on tumor cells induces expression of PDPN on macrophages, which promotes migration of PDPN+ macrophages to lymphatic endothelial cell structures, thereby promoting lymphangiogenesis." (PMID 38426622, 2024). "Ultimately, tissue microarray analysis (TMA) with 63 HNSCC samples confirmed the positive correlation of higher expression of SEMA7A in tumor cells (high: positive ratio ≥ 20%; low: positive ratio <20%) with poorer prognosis." (PMID 38548747, 2024).
tumor (continued). "PLXNC1 is a receptor for the SEMA7A protein, which regulates a wide range of tumor cell functions, including proliferation, invasion, migration, and angiogenesis." (PMID 39001376, 2024). "In vitro proliferation analysis demonstrated that deglycosylation of SEMA7A dramatically decreased cell viability and was negatively correlated with tumor invasion in both HN6 and HN30 cells." (PMID 38548747, 2024). "We subsequently investigated the potential associations between the expression levels of SEMA7A, SEMA4D, ADAM8, and ADAMTS10 proteins and the characteristics of tumor size (T), lymph node involvement (N), metastasis (M), and disease stage." (PMID 39329961, 2024). "Among the studied proteins in our study, we observed significantly elevated levels of SEMA7A protein in BRAF-mutant tumors compared to the BRAF wild-type tumor group." (PMID 39329961, 2024). "Subsequently, high enrichment of these molecules was further verified in 5 HNSCC cell lines, along with the finding that SEMA7A presented marked upregulation in all cell types, indicating its participatory role in tumor progression." (PMID 38548747, 2024). "The current investigation focused on exploring the underlying mechanism of aberrant glycosylation of SEMA7A in HNSCC and its role in tumor progression, EGFR-targeted therapy, immunotherapy, and splicing regulation." (PMID 38548747, 2024). "In clinical samples analysed by TCGA, the expression of 5 genes, CCL20, IL1B, IL24, PLAU and SEMA7A, was significantly higher in the primary tumour than in solid normal tissue, whereas that of CITED2 was lower." (PMID 38363001, 2024). "Sema7a can mediate macrophage and dendritic cell migration and tumor lymphatic metastasis through integrin-β1 receptors." (PMID 38022556, 2023). "Black found that SEMA7A plays an essential role in degenerating mammary glands and that SEMA7A promotes PPBC progression by regulating tumor-associated COX-2 expression and fibroblast-mediated collagen deposition in the tumor microenvironment." (PMID 37555951, 2023). "FAK/ERK1/2 acts as a downstream signal pathway of the Sema7a-integrin-β1 axis, which mediates vascular endothelial dysfunction and tumor metastasis." (PMID 38022556, 2023). "Multivariate Cox regression analysis further demonstrated that a more advanced stage and grade of tumor and higher SEMA7A mRNA expression were independent unfavorable prognostic factors of OS (p < 0.0001)." (PMID 35955933, 2022). "On the other hand, the factors uniquely enriched in GEC (IL23A and WNT16B) and GPC (IL33 and SEMA7A) significantly promoted proliferation of radiated (8 Gy mC-) tumor cells only." (PMID 36261421, 2022). "Recent studies revealed a tumor-promoting role of Sema7A during postpartum mammary gland involution 30,31." (PMID 33537086, 2021). "SEMA7A/Plexin-C1 mediated cofilin inactivation led to the identification of Plexin-C1 as a novel tumor suppressor." (PMID 30847405, 2019). "The authors also examined the effects of Sema7A silencing using shSema7A as a potential anti-tumor therapeutic measure." (PMID 30134791, 2018). "Mechanistically, Sema7A seems to act both on tumor cells to increase invasion as well as on TAM to induce the release of proangiogenic molecules." (PMID 29141914, 2018). "We found that while PEMs from normal mice express low levels of SEMA7A, the expression of this protein is increased in PEMs from tumor bearers." (PMID 24550834, 2014). "Although DA-3 cells express lower levels of CXCL2/MIP-2 compared to macrophages, silencing the SEMA7A gene also lead to a decrease in tumor-derived CXCL2/MIP-2." (PMID 24550834, 2014). "We then asked if SEMA7A is expressed by EpH4 mammary cells, a normal mammary cell line, and how do these levels compare with those in DA-3 tumor cells?" (PMID 24550834, 2014). "We therefore tested to see if SEMA7A gene silencing in tumor cells has an effect on CXCL2/MIP-2 chemokine expression." (PMID 24550834, 2014).